PDZD2 (PDZ domain containing 2)
Synonyms: AIPC; KIAA0300; PDZK3; PAPIN
Tractability: Antibody: its Gene Ontology location is reachable by antibodies, with high confidence; UniProt places it where antibodies can reach, with medium confidence; the Human Protein Atlas places it where antibodies can reach. PROTAC: ubiquitination databases record sites on it.
Gene: Protein-coding gene on chromosome 5 (31,639,121 to 32,110,933, forward strand). Ensembl gene ENSG00000133401.
Subcellular location: Nucleus; Cytoplasm; Endoplasmic reticulum; Secreted (Processed PDZ domain-containing protein 2)
Subcellular location (Human Protein Atlas): Cytosol; Plasma membrane
Gene Ontology:
Molecular function: protein binding
Cellular component: cytoplasm; cytosol; plasma membrane; cell-cell junction; endoplasmic reticulum; extracellular region; nucleus
Genetic constraint (gnomAD): Loss-of-function variants: 66 observed, 173.41 expected, observed/expected ratio (o/e) 0.38, 90% interval 0.31 to 0.47. The upper end of that interval is the gene's LOEUF score, 0.47, which puts it in group 2 of 6, group 1 being the genes least tolerant of losing a copy. Missense variants: 2,797 observed, 3,292.6 expected, observed/expected ratio (o/e) 0.85, 90% interval 0.82 to 0.88. Synonymous variants: 1,215 observed, 1,352 expected, observed/expected ratio (o/e) 0.9, 90% interval 0.86 to 0.94.
Homologues: Orthologues: chimpanzee PDZD2 (99% identical), macaque PDZD2 (93% identical), guinea pig PDZD2 (72% identical), dog PDZD2 (70% identical), rat Pdzd2 (69% identical), mouse Pdzd2 (69% identical), tropical clawed frog pdzd2 (37% identical), zebrafish pdzd2 (32% identical). Paralogues in human: IL16 (13% identical).
Diseases named in the same sentence as PDZD2 in open-access papers:
PDZD2 is named in the same sentence as 34 diseases in open-access papers, as found by Europe PMC text mining. Sharing a sentence is not in itself a finding about the gene and the disease. The quoted sentences say what the papers report.
osteosarcoma (4 papers, 2019 to 2022). A usually aggressive malignant bone-forming mesenchymal neoplasm, predominantly affecting adolescents and young adults. "LncRNA PURPL affected tumor-associated macrophages through modulating miR-363 and PDZD2 in osteosarcoma cells." (PMID 35992869, 2022). "Previous studies have suggested that PDZD2 is an oncogene, which is over-expressed in the cell lines of osteosarcoma, human primary prostate tumor and prostate tumor." (PMID 35433681, 2022).
prostate carcinoma (3 papers, 2013 to 2023). A carcinoma that arises from epithelial cells of the prostate gland. "PDZD2 may be involved in intracellular signaling and is overexpressed in prostate cancer and associated with the initiation or early events in tumourigenesis." (PMID 23433318, 2013).
asthma (2 papers, 2013 to 2018). "Of the top two regions, KCNIP4 and PDZD2/GOLPH3/MTMR12/ZFR, only KCNIP4 had gene-level replication in the SHARP AHR GWAS at a nominally significant level in the same regions as the asthma GWAS studies." (PMID 23457522, 2013).
breast carcinoma (2 papers, 2023).
diabetes (2 papers, 2016 to 2024). "Although PDZD2 is mostly implicated in pancreatic development, it is important to highlight that diabetes is an established risk factor of AD and further study on PDZD2 could uncover correlations with Alzheimer’s disease." (PMID 38472245, 2024). "Foremost, all four patients were affected by a homozygous, compound heterozygous mutations or de novo variant in a diabetes-relevant (CLTCL1 and PDZD2) or pancreatic expressed (MORN1 and ZNF330) gene." (PMID 28007035, 2016).
chronic gastritis (1 paper, 2015). Inflammation of the stomach that is chronic in nature. "We noticed that 6 somatic variations (ATXN3, PLIN4, PDZD2, MUC4, DMBT1 and DAB1) were simultaneously observed in triple samples of chronic gastritis, primary cancer and PM cancer." (PMID 26330360, 2015).
Cognitive impairment (1 paper, 2024). Abnormal cognition is characterized by deficits in thinking, reasoning, or remembering. "The identification of PDZD2 and NEURL1 genes, which have been linked to cognitive impairments related to learning and memory, serves as supportive evidence for the efficacy of the models employed." (PMID 38472245, 2024).
cutaneous melanoma (1 paper, 2022). A primary melanoma arising from atypical melanocytes in the skin. "We found that PDZD2 was poorly expressed in cutaneous melanoma." (PMID 35433681, 2022).
heart failure (1 paper, 2023). Inability of the heart to pump blood at an adequate rate to meet tissue metabolic requirements. "SNPs in the PDZD2 gene have been associated with heart rate in heart failure patients with reduced ejection fraction." (PMID 37408649, 2023).
insulinoma (1 paper, 2016). "Furthermore, higher concentrations of secreted PDZD2 in rat insulinoma cell lines were correlated with higher rates of cell proliferation and inhibited transcription of INS, an insulin promoter." (PMID 28007035, 2016).
lung adenocarcinoma (1 paper, 2022). A carcinoma that arises from the lung and is characterized by the presence of malignant glandular epithelial cells. "Recently, it has been shown that human secreted PDZD2 (sPDZD2) has anti-tumor properties, and it is also down-regulated in lung adenocarcinoma." (PMID 35433681, 2022).
melanoma (1 paper, 2022). A malignant, usually aggressive tumor composed of atypical, neoplastic melanocytes. "Among them, only PDZD2, NPY1R and ADH1B have not been reported in melanoma studies, and EMP3 has only been reported in uveal melanoma." (PMID 35433681, 2022).
myocardial infarction (1 paper, 2020). Gross necrosis of the myocardium, as a result of interruption of the blood supply to the area, as in coronary thrombosis. "The genetic variant in the PDZD2 DMR was previously associated with myocardial infarction." (PMID 31999706, 2020).
myopia (1 paper, 2010). "Six candidate genes CDH6, CDH10, CDH12, PDZD2, GOLPH3, and ZFR at this high myopia locus were selected on the basis of their function to screen for gene mutations by re-sequencing." (PMID 21042559, 2010).
papillary thyroid cancer (1 paper, 2022). "Finally, we investigated the expression levels of the common mutated genes (JMJD1C, MUC16, PDZD2, RYR1, and SLA) in papillary thyroid cancer cell lines (K1, TPC-1 and BCPAP) compared to an immortalized normal thyroid epithelial cell line (Nthy-ori 3-1) by qRT-PCR." (PMID 35996174, 2022).
pneumonitis (1 paper, 2022). An inflammatory process affecting the lung parenchyma. "Several of these filtered candidates were found to be secreted (C12orf49, COL10A1, FNDC4, ITLN2, MATN3, PDZD2, RS1, SCRG1, and ST6GALNAC5) making them potential candidate biomarkers useful for distinguishing IPF from pneumonitis." (PMID 35628257, 2022).
spastic ataxia (1 paper, 2014). "One of the nonsynonymous SNVs is in the gene PDZ domain containing 2 (PDZD2) on chromosome 5; the other is in gene spastic ataxia of Charlevoix-Saguenay (sacsin) (SACS) on chromosome 13." (PMID 25519376, 2014).
thyroid cancer (1 paper, 2022). "We found that the high impact mutations in JMJD1C, SLA, PDZD2, identified from in-silico analysis in PTC samples, are missing in the thyroid cancer cell lines analyzed, thus suggesting that the altered expression of these genes is due to other regulative biological mechanisms." (PMID 35996174, 2022). "The analysis showed that the gene expression level of JMJD1C, MUC16 and SLA were statistically down-regulated while the gene expression level of PDZD2 and RYR1 were up-regulated in thyroid cancer with respect to normal thyroid tissues." (PMID 35996174, 2022).
thyroid tumor (1 paper, 2022). A benign or malignant neoplasm affecting the thyroid gland. "We aimed to evaluate the common mutated genes (JMJD1C, MALAT1, MUC16, PDZD2, PKHD1, RYR1, SLA and TTN) between thyroid tumor and normal samples." (PMID 35996174, 2022).
tumor (10 papers, 2014 to 2025). "They enhance OS aggressiveness by upregulating the lncRNA PURPL/miR-363/PDZD2 axis, which suppresses miR-363 to elevate PDZD2 expression, thereby driving tumor proliferation, invasion, and EMT." (PMID 40941019, 2025). "As demonstrated in our previous research, miR-363 played a tumor inhibitory effect in OS cells via lowering the PDZ domain containing 2 (PDZD2) expression." (PMID 34686652, 2021). "As indicated in our previous experiments, miR-363 exerted tumor inhibitory activity in OS cells via suppressing the PDZ domain containing 2 (PDZD2) expression." (PMID 34686652, 2021). "The difference of PDZD2 expression in different tumor tissues may be related to tissue specificity." (PMID 35433681, 2022).
cancer (4 papers, 2014 to 2024). A tumor composed of atypical neoplastic, often pleomorphic cells that invade other tissues. "As cancer advances, TBX3 may further control the aberrant behavior of cell adhesion molecules, synergizing with PDZD2 to contribute to the spread of OS." (PMID 38911382, 2024).
prostate (2 papers, 2014 to 2019). "PDZD2 and its secreted form (sPDZD2) are possibly involved in functional maturation of human fetal PPC-derived ICCs and the early stages of prostate tumorigenesis." (PMID 25519376, 2014).
PDZD2 also shares sentences with these, for which no sentence is quoted: Alzheimer disease (1 paper); clear cell renal cell carcinoma (1); colon cancer (1); colorectal cancer (1); gastric cancer (1); liver cancer (1); metastatic cancer (1); neurodegenerative disease (1); preeclampsia (1); pregnancy disorder (1); prostate tumor (1); uveal melanoma (1).